TNF (tumor necrosis factor)
Diseases named in the same sentence as TNF in open-access papers (continued):
Sharing a sentence is not in itself a finding about the gene and the disease.
tumor (continued). "In addition, the M2d TAMs also secrete TNF to promote tumor cell glycolysis, thus providing additional oxygen to the hypoxic tumor cell and further contributing to cancer dissemination." (PMID 32283687, 2020). "The results indicate a composite tumor suppressor role for SMG7 in response to TNF." (PMID 32602581, 2020). "In addition, the same experiments using cGAS or TNF KO cells in vivo showed that either depletion deeply impaired paclitaxel tumor response." (PMID 31937780, 2020). "The majority of tumor-reactive TILs expressed CD107a or secreted TNF." (PMID 32127601, 2020). "In immunotherapy it is hypothesized that, due to the systemic inflammation initiated by the tumor itself, the increased infiltration of neutrophils promotes cancer progression via secreting interleukin-10 (IL-10), tumor necrosis factor α (TNF-α), and VEGF." (PMID 33272262, 2020). "B16F10 tumor cells expressed high levels of TNFα and moderate levels of IFNβ after irradiation." (PMID 33202881, 2020). "Both MC subtypes produce TNF-α which plays a role in anti-tumor immune responses." (PMID 32086776, 2020). "Importantly, increased level of tumor necrosis factor alpha (TNF-α) was also observed after DMONs treatment, which is an important marker for anti-tumor immunity." (PMID 32408880, 2020). "Supporting this idea, it has been reported that aberrant elevated TNFα levels might promote not only tumor growth, but also invasion and poor prognosis." (PMID 32256215, 2020). "However, c-Met expression on neutrophils induced by tumor-derived TNF-α or other inflammatory stimuli is required for neutrophil chemoattraction and cytotoxicity in response to HGF." (PMID 33101283, 2020). "Higher levels of TNF-α and IL-1β are also found in tumor-independent areas of tissue metastases." (PMID 33718121, 2020). "Different types of cancer, including breast cancer, prostate cancer, decidual malformations, leukemia, and lymphoma, can be altered by NK cell functions by modifying tumor microenvironment components such as the tumor necrosis factor alpha, acidics, tumor exosomes, hypoxia, and adenosine." (PMID 33371393, 2020). "In addition, our preliminary data showed the upregulation of the expression of TNF signaling genes and protein processing genes in VV-iPDL1/GM-infected tumor cells by RNA-Seq and qRT-PCR." (PMID 32170083, 2020). "TNF-α has a receptor on tumor cells that stimulates activation and prolonged expression of the JUN oncogene; participates in apoptosis; stimulates the hydrolysis of sphingomyelin, ceramide, and phosphorylcholine; and induces the production of reactive oxygen species." (PMID 32102503, 2020). "Furthermore, we found that TNFα maintained sustainable growth sharply after tumor became resistant to bevacizumab." (PMID 33214550, 2020). "Likewise, tumor-associated CD103+CD4 TRM have been described to be highly enriched for tumor-specific T cells and suppress tumor growth through the secretion of TNF-α and IFN-γ or direct killing of tumor cells." (PMID 32973794, 2020). "Indeed, restricted p50 translocation into nucleus limits the formation of the immunosuppressive p50:p50 homodimers in favor of the p65:p50 inflammatory heterodimers that sustain an increased release of TNFα in the tumor microenvironment." (PMID 32133298, 2020). "It has been revealed that the inhibition miR-106a and miR-591 expression decreased the level of tumor cells resistance to paclitaxel, as both types of miRNAs are involved in the regulation of pro-apoptotic genes, such as tumor necrosis factor (TNF) ligand/receptor and caspase families." (PMID 31936634, 2020). "Thus, we identify TNF-α/IL-33/ST2L signaling as a mediator of the tumor–stromal cell interaction in GC." (PMID 31659258, 2020). "Therefore, various combinations have been investigated to safely enhance the levels of TNF experienced by the tumor by targeting other signaling pathways, or using chemo-, radiation or immunotherapy." (PMID 32053868, 2020).
tumor (continued). "A study showed that SLPI has the ability to decrease the liver-metastasizing potential of tumor cells and this effect may be attained by reducing the production of hepatic TNF-α and E-selectin." (PMID 32076707, 2020). "TNF-α serves a dual role in tumor proliferation and apoptosis." (PMID 33292267, 2020). "In addition, TNF has been shown to enhance the antitumor effects of a variety of other anticancer drugs by increasing drug penetration into tissues and destroying tumor vasculature." (PMID 32027657, 2020). "TNF-α, originally described for its anti-tumour properties, is a multifunctional cytokine, which, at high doses, can induce tumour cell apoptosis whereas it accelerates tumour progression via tumour invasion and metastasis with chronic low doses." (PMID 32168834, 2020). "TNFα inhibits angiogenesis and accelerates the clotting of blood feeding the tumor." (PMID 33266223, 2020). "Indeed, TNF can trigger pro-tumour functions, including tumour cell proliferation, invasiveness, Epithelial to Mesenchymal Transition (EMT), angiogenesis, the recruitment of tumour-promoting and the elimination of tumour-suppressive immune cells." (PMID 32365592, 2020). "In conclusion, EMAP II not only exerts antitumor effects by inducing autophagy of tumor cells, inhibiting angiogenesis, sensitizing tumor cells to TNF-α, and increasing the permeability of BTB, but also promotes the development of cancer by inducing lymphocyte apoptosis." (PMID 32709848, 2020). "Moreover, CXCR2 ligands (CXCL1, 2, and 5) induced by TNF-α-activated MSC recruit CXCR2+ neutrophils into tumor, responsible for the pro-metastatic effect of MSC." (PMID 32499779, 2020). "Conversely, low levels of TNF-α production can induce a tumor phenotype." (PMID 32283655, 2020). "Additionally, miR‐328‐3p neutralized the elevated levels of TNF‐α and IL‐6 induced by hsa_circRNA_002178 in tumour tissues and serum." (PMID 31957232, 2020). "Besides the detrimental effect of IL-17A, the pro-inflammatory cytokine TNF also plays a role in intestinal polyp formation in the APCΔ468 mouse model and TNF blockade diminishes tumor development." (PMID 32185408, 2020). "Thus, TNF derived from infiltrated dendritic cells in tumor microenvironment would likely promote neuropathic pain with cancers." (PMID 32434423, 2020). "Combination therapies that enhance the efficacy of SMs are those that typically increase the local concentration of inflammatory cytokines, which can then be harnessed and potentiated by SMs via their capacity to sensitise tumour cells to TNF-mediated apoptosis." (PMID 31947615, 2020). "One study suggested that TNF in Dexs could kill tumor cells by activating NK cells and inducing the secretion of IFN-γ." (PMID 33374978, 2020). "Newly tumor-infiltrated naive M0 macrophages exert anti-tumorigenic activities via TNF-α secretion." (PMID 33267818, 2020). "Chlorine e6 and doxorubicin-loaded hollow manganese dioxide nano platform (H-MnO2-PEG/C&D) will alleviate tumor suppression, although checkpoint blocking (PD-L1 blocking) promotes higher TNF-α secretion and improved immune response of CD4 + and CD8 + T cells that chemo-PDT therapy." (PMID 32865029, 2020). "PC cells-derived TNF-α enhances the tumor cell growth and invasiveness both in vitro and in vivo." (PMID 32012917, 2020). "Furthermore, TCRγδCD8− T cells secreting both IL-17A+ and TNF+ are significantly increased in tumor tissue, compared to unaffected tissue." (PMID 32185408, 2020). "We found IFNγ and TNFα, two major cytokines in tumor microenvironment, could induce programmed death-ligand 1 (PD-L1) expression in MSCs." (PMID 32509271, 2020).
tumor (continued). "TNF-α is a multifunctional cytokine that modulates various phases of cancer cell phenotypes, for example cell propagation, migration, invasion, as well as instigating the death of tumor cells." (PMID 32194791, 2020). "Moreover, stimulating STING-dependent type-I IFN and TNFα signals simultaneously can lead to necroptosis of tumor cells." (PMID 32411126, 2020). "Furthermore, fruti induced necrosis and apoptosis, increased N-acetyl-β-D-glucosaminidase and TNF-α levels and reduced IL-10 and Vegf levels in tumor tissue." (PMID 33020521, 2020). "However, inhibition of TACE/ADAM-17 reduces mTNFα shedding on IFN-DC membranes and enhances the cytotoxic DC activity against TNFα/TNF-R1-sensitive tumor cells." (PMID 32326230, 2020). "The tumor‐associated CD4/CD8 double‐positive T (DPT) cells are found enriched in L regions with synergetic expression of PD‐1/HLA‐DR/ICOS/CD45RO and exhibit a higher level of IFN‐γ, TNF‐α, and PD‐1 upon stimulation." (PMID 32670760, 2020). "This implies that any tumor-promoting effects of TNF-α inhibition may become apparent from epidemiological analyses in the years to come." (PMID 33267818, 2020). "In mice, TNF can promote EZH2 expression in tumor cells and trigger tumor recurrence." (PMID 32000802, 2020). "In PDA animal models, we identified that either engineered or endogenous intratumoral tumor antigen-specific T cells also become defective in their production of IFNγ, TNFα and expression of cytolytic molecules including Granzyme B following specific peptide recognition." (PMID 33584701, 2020). "This means that an amplification loop of the effects of cyH on tumor inflammation exists, as TNFα secreted in higher amount by cycling hypoxic macrophages could target endothelial cells and as cyH amplifies the endothelial inflammatory response to TNFα." (PMID 31964911, 2020). "The aim of the present study was to measure the tumor TNF-alpha, interleukin-1 beta (IL-1 beta), adiponectin, and adropin levels that play a role in systemic inflammation in OSAS patients for determining whether they are related to OSAS or not." (PMID 32454912, 2020). "Altogether, these data in cultured human CD8 T cells reveal that the use of TNF blocking agents could improve the viable fate of tumor- and antigen-specific CD8+ T cells following cognate antigen encounter." (PMID 32292509, 2020). "Among these substances is TNF-α, capable of inducing apoptosis in tumor cells." (PMID 33262947, 2020). "Recent studies have shown that hsa-miR-130b-3p acts as a tumor suppressor, inhibiting cancer angiogenesis by specifically targeting tumor necrosis factor-α (TNF-α), thereby suppressing the nuclear factor-κB/vascular endothelial growth factor-A (NF-κB/VEGFA) signaling pathway." (PMID 32423052, 2020). "Similarly, genetically modified MSCs expressing tumor necrosis factor (TNF)-related apoptosis-inducing ligand (TRAIL) were shown to induce apoptosis in several tumor types." (PMID 32560387, 2020). "This system allows delivery of TNF directly to the tumor tissue, minimizing systemic toxicity." (PMID 32053868, 2020). "The intratracheal administration of these bacterial formulations led to the enhanced immune cell migration (neutrophils and leucocytes) into the tumor microenvironment and the lung tumor tissues showed higher levels of TNF-α, IL-4, and IFN-γ than healthy lung tissues." (PMID 33066447, 2020). "Therefore, we thought that TNFα is a key tumor-promoting effector molecule secreted by M2b macrophage." (PMID 33214550, 2020). "Chronic exposure to antigen in the tumor microenvironment leads to high expression of inhibitory receptors, such as PD-1, TIM-3, CTLA-4, and LAG-3, as well as a gradual loss of the ability to produce effector cytokines (IFN-γ, TNF-α, and IL-2) and proliferate." (PMID 32391270, 2020).
tumor (continued). "Also, cytokines that include TNF‐α and IL‐6 are related to the inflammation process and known to typical proinflammatory cytokine with tumor growth effect (Landskron, De la Fuente, Thuwajit, Thuwajit, & Hermoso, 2014)." (PMID 32328255, 2020). "Indeed, several studies demonstrate either a pro-tumor or anti-tumor role for pro-necroptotic genes (frequently tested through genetic knock-out or knock-down models) and/or necroptosis (induced via TNF/TRAIL-based ‘cocktails’ or genetic means)." (PMID 32752206, 2020). "TNF-α, produced by adipose tissue and inflammatory cells, can lead to inflammatory response, necrocytosis, and assist other cytokines to kill tumor cells, and improve the anti-tumor ability." (PMID 32819324, 2020). "Hence, restoring the ability of tumor associated pDCs to produce IFN-α in combination with TLR7/9-based immunotherapy with TGF-β and TNF-α antagonists can restore the antitumor immunity in breast cancer patients." (PMID 32784928, 2020). "A possible explanation behind the positive effect of eosinophils is their capacity to recruit cytotoxic T lymphocytes through CCL5, CXCL9, and CXCL10, to induce an anti-tumor phenotype in macrophages through TNFα and IFNγ and to normalize the tumor vasculature." (PMID 32793228, 2020). "Microglia are essential for tissue repair processes and the maintenance of homeostasis during infectious diseases, ischemic lesions, and tumor growth, which can activate the over-expression of proinflammatory cytokines, e.g., TNF-α, IL-1β as well as neurotoxic radicals, e.g., ROS, nitric oxide." (PMID 33628177, 2020). "It has already been demonstrated that TNF-α exhibits low expression in fibroblast and tumor cells." (PMID 31936364, 2020). "When it comes to neoplasia, TNF-α has an ambivalent role, as it could be both an enhancer and a tamer of cancer." (PMID 33228048, 2020). "The presence of inflammatory cytokines, like interferon γ (IFNγ), interleukin-17 (IL-17) or tumor necrosis factor α (TNFα), but also oncogenes or tumor suppressors can activate the NF-κB-dependent pathway leading to PD-L1 upregulation and maintenance of immune checkpoint blockade." (PMID 32486375, 2020). "Neutrophilia provide a favorable tumor microenvironment for cancer progression by secreting many inflammation mediators such as tumor necrosis factor alpha (TNF-α), vascular endothelia growth factor (VEGF), interleukin-2 (IL-2), interleukin-6 (IL-6), and interleukin-10 (IL-10)." (PMID 32911724, 2020). "Cross-linking and tumour antigen-specific IgE antibody-dependent cellular cytotoxicity (ADCC) of cancer cells by cancer patient-derived monocytes triggered release of pro-inflammatory mediators (TNFα, MCP-1, IL-10, CXCL-10, IL-1β, IL-6, IL-23)." (PMID 33203088, 2020). "Indeed, tumor cells themselves are able to produce TNFα and can increase its concentration upon therapy insults such as chemo/radiotherapy, targeted therapies and immunotherapy with ICB, to take advantage of NF-κB signaling to promote survival." (PMID 32391269, 2020). "A high RDW may be driven by the excessive production of cytokines in the tumour microenvironment, such as IL-6 and TNF-a." (PMID 32705478, 2020). "Since Trichomicin downregulated TNFα expression in tumor tissues and TAMs, we examined whether Trichomicin could inhibit TNFα–induced NF-κB activation in HCT-116 cells." (PMID 32317968, 2020). "Indeed, previous work reported that TNF-α contributes to anti-tumor activities, mediating both direct and indirect cytotoxic functions." (PMID 32443460, 2020).
tumor (continued). "Within the tumor microenvironment, cancer cells and interacting host cells produce a battery of pro-inflammatory cytokines, such as tumor necrosis factor alpha (TNF-α) and Interleukin 6 (IL-6), among many others, that play a central role in the induction and in the course of cancer cachexia." (PMID 32083092, 2020). "Similarly, higher levels of TNF-α are often related with tumor progression, whereas anti-TNF-α therapy is commonly administered to RCC patients." (PMID 32714856, 2020). "A handful of studies utilized various stimuli known to induce TAp73 expression, including DNA-damaging conditions such as irradiation, etoposide, doxorubicin, and cisplatin treatment, or tumor-promoting conditions such as hypoxia, tumor necrosis factor (TNFα) treatment, and serum stimulation." (PMID 32079264, 2020). "However, HPSE has been shown to regulate tumour necrosis factor (TNF) expression, a key enabler of necrosis, whose superfamily members possess pro-tumorigenic and pro-tumour inflammatory activity." (PMID 33256730, 2020). "Thus, in both HCC tumor models, entolimod reduced the toxicity of TNF/D-GalN while preserving its tumor growth suppressive effects." (PMID 32027657, 2020). "TNF-α exhibits tumoricidal effects by inducing apoptosis and hemorrhagic necrosis of tumor cells." (PMID 32917034, 2020). "AIMP2 had multidirectional tumor-suppressive activity, which mediated the apoptotic response to DNA damage, tumor necrosis factor α (TNF-α)-induced cell death and sensitivity to anti-proliferative transforming growth factor-β (TGF-β) signal in a dose-dependent manner." (PMID 33330488, 2020). "The role of tumor necrosis factor-α (TNF-α) in shaping the tumor microenvironment is ambiguous." (PMID 33202705, 2020). "Macrophages are the main cell types secreting TNF and therefore involved in tumor formation in CRC." (PMID 32171282, 2020). "TNFα can also be induced by single-fraction irradiation in tumor cell lines." (PMID 33050580, 2020). "The immune reaction to antitumor was intensified by photodynamic therapy (PDT), where it effectively eradicated the tumor and remote metastasis in the B16-F10 melanoma model through encouraging cytokine production (TNF-α and IFN-ÿ) and tumor invasion lymphocyte frequency (CD8+ and CD4+)." (PMID 32865029, 2020). "A good example is that tumor cells could be lysed by incubating them with transmembrane TNFα on paraformaldehyde-fixed activated macrophages." (PMID 33396603, 2020). "Therefore, we determined tumor cytokine expression of type 1 (TNF-α and IFN-γ), type 2 (IL-4 and IL-5), and regulatory (IL-10) cytokines." (PMID 32547942, 2020). "Moreover, TNF-α was initially found to induce apoptosis in different cancer types by tumor-promoting activities including transformation, proliferation, invasion and metastasis of cancer cells." (PMID 33187552, 2020). "In addition, they demonstrated that TNF-α needs to be used in conjunction with chemotherapy to enhance ROS in tumor sites through mechanisms such as NADPH oxidase." (PMID 35492191, 2020). "As with TNF-α and IL-1β, IL-18 may also exhibit both pro- and anti-tumour activity in CRC, depending on the stage of progression and immune effector cells responsive to IL-18." (PMID 32168834, 2020). "In the tumor, however, they were significantly higher in the infiltrated CD4+ and CD8+ T cells of Lsp1 KO mice than in those of WT mice, suggesting that Lsp1 deficiency increases antitumor immunity by inducing TNF-α+ and IFN-γ+ expression in tumor-infiltrating T cells." (PMID 33020243, 2020). "Moreover, several factors that induce tBregs are found in the tumor microenvironment, including TNF-α (secreted by tumor cells) and IL-21 (secreted by T cells)." (PMID 31248034, 2019). "Moreover, this study showed that elevation of serum inflammatory cytokines (TNFα and IL-6) in tumor-bearing mice are in sync with and dependent on the elevation of serum Hsp70 and Hsp90." (PMID 31480237, 2019).